ABCG2 (ATP binding cassette subfamily G member 2 (JR blood group))
Diseases named in the same sentence as ABCG2 in open-access papers (continued):
Sharing a sentence is not in itself a finding about the gene and the disease.
cancer (continued). "In summary, we revealed that the second-generation PIM kinase inhibitor TP-3654 resensitizes ABCG2-overexpressing multidrug-resistant cancer cells to cytotoxic anticancer drugs by attenuating the drug efflux function of ABCG2." (PMID 34502348, 2021). "Although overexpression of other ABC transporters, including MRP1/ABCC1, has also been implicated in cancer MDR, this review focuses on P-gp and ABCG2." (PMID 34993424, 2021). "Of these, ABCB1 and ABCG2 appear to be the most important in the mediation of the MDR phenotype in cancer cells when overexpressed." (PMID 33573093, 2021). "The ATP-binding cassette (ABC) transporters P-glycoprotein (P-gp) and ABCG2 are multidrug transporters that confer drug resistance to numerous anti-cancer therapeutics in cell culture." (PMID 34993424, 2021). "In this study, we investigated the potential role of the multidrug efflux transporters ABCB1 and ABCG2, which are two of the most common mechanisms of acquired resistance to anticancer drugs, on the efficacy of citarinostat in human cancer cells." (PMID 33807514, 2021). "To this end, we examined the effect of TP-3654 on the protein expression of ABCG2 in ABCG2-overexpressing cancer cells." (PMID 34502348, 2021). "The rate of SP cells in the LuM1 cells’ population was 7.8%, while that in Colon26 was lower (2.9%), suggesting that the ABCG2 positive SP rate was positively correlated with the metastatic potential of the cancer cell population." (PMID 33562088, 2021). "While the role of ABC transporters, including P-gp and ABCG2, has been studied extensively in vitro, there is still much to learn about the clinical importance of ABC transporter expression in cancer." (PMID 34993424, 2021). "More significantly, TP-3654 selectively interferes with drug transport mediated by ABCG2 and resensitizes ABCG2-overexpressing cancer cells to cytotoxic anticancer drugs." (PMID 34502348, 2021). "The anti-cancer agents doxorubicin and daunorubicin have also been reported as ABCG2 substrates, but eventually it was revealed that these drugs are transported only by the R482G ABCG2 variant." (PMID 33801813, 2021). "In conclusion, our results revealed a novel mechanism by which ABCB1 and ABCG2 actively transport citarinostat away from targeting HDAC6 in cancer cells." (PMID 33807514, 2021). "Unexpectedly, the endogenous low expression of ABCG2 is sufficient to confer cancer cells resistance to MLN7243." (PMID 34336849, 2021). "Conversely, the silencing of GLI or OPN reversed EMT by reducing mesenchymal markers and increasing epithelial marker (keratin 18) expression, decreased ABCB1 and ABCG2 expression, and restored chemosensitivity to cancer chemotherapeutics." (PMID 34638233, 2021). "We discovered that the overexpression of ABCB1 or ABCG2 significantly reduced the sensitivity of human cancer cells to citarinostat." (PMID 33807514, 2021). "The reversal efficacy of VKNG-1 in S1-M1-80 cancer cells is because of its blockade of the ABCG2 transporter efflux function and downregulation of the ABCG2 protein." (PMID 34572902, 2021). "The cell viability assay indicated that the effect of OTS964 is limited in cancer drug-resistant and transfected cells overexpressing ABCG2." (PMID 33658942, 2021). "There are efflux pumps such as multidrug resistance-associated proteins (MRP), noted ABCC1 and breast cancer resistance proteins, renamed ABCG2 and mitoxantrone resistance proteins (BCRP, MXR)." (PMID 33567616, 2021). "ABCG2 is overexpressed on the plasma membrane of various types of cancer cells functioning as an efflux pump to excrete a broad spectrum of chemotherapeutic drugs." (PMID 33829017, 2021). "For instance, ABCG2, an indicator of cancer stemness, is highly involved in acquiring multidrug resistance to cancer chemotherapeutics such as Cisplatin and Etoposide." (PMID 34059086, 2021).
cancer (continued). "In premenopausal samples (n = 11) statistically significant changes were observed for only one gene, ABCG2, which was 5.9-fold down-regulated in cancer compared to adjacent control tissue." (PMID 33917029, 2021). "ABC transporter G2 (ABCG2) is a drug resistance protein, also called a breast cancer resistance protein (BCRP), as well as a stem cell marker, including cancer stem cells." (PMID 33562088, 2021). "Several studies have established that cancer stem-like cell (CSC) population in cancer expressing ABCG2 limits the efficacy of chemotherapy and is responsible for the reemergence of tumors during the period of relapse in various cancer patients." (PMID 34572902, 2021). "Compared to the S1 cancer cell line, the resistant-fold values of the drug-resistant cancer cells to the ABCG2 specific substrate antineoplastic drugs mitoxantrone, SN-38 and doxorubicin, were significantly reduced by 1.6, 2.2 and 0.5-fold, respectively." (PMID 34572902, 2021). "In this study, we discovered that by attenuating the drug transport function of ABCG2, TP-3654 resensitizes ABCG2-overexpressing multidrug-resistant cancer cells to cytotoxic ABCG2 substrate drugs topotecan, SN-38 and mitoxantrone." (PMID 34502348, 2021). "In this way, we also found the mRNA levels of cancer stemness-associated molecules, including POU5F1, Slug and ABCG2, were significantly decreased by melatonin treatment in both LoVo and DLD-1 cell lines." (PMID 34671196, 2021). "More recently, another member of the ABC superfamily that has been shown to confer multidrug resistance in cancer cells in culture is the BCRP or ABCG2." (PMID 34993424, 2021). "ABCG2-mediated MDR can significantly attenuate or abrogate the efficacy of anticancer drugs by increasing their efflux from cancer cells." (PMID 33671108, 2021). "First, the anti-cancer drug mitoxantrone has been demonstrated to be exported by ABCG2, thus reducing its intracellular accumulation." (PMID 33801813, 2021). "Our data demonstrated that the intracellular concentration of citarinostat and the HDAC6 inhibiting activity were significantly reduced by ABCB1 and ABCG2, and consequently, cancer cells overexpressing ABCB1 or ABCG2 are insensitive to citarinostat." (PMID 33807514, 2021). "ABCG2 is expressed in CD133-positive cancer stem cells (CSCs) from human colorectal tumors; accordingly, it is considered a marker for such types of CSCs cancers." (PMID 34680470, 2021). "A similar behavior was observed, confirming that a partial inhibitor can chemosensitize cancer cells overexpressing ABCG2." (PMID 33469044, 2021). "Numerous in vitro studies have demonstrated altered efflux of chemotherapeutic agents and reduced drug resistance in cancer cells expressing ABCG2 carrying various SNPs." (PMID 33801813, 2021). "In conclusion, our study suggests that in vitro, GS-9973 in combination with certain anticancer drugs, represent a strategy to overcome ABCG2-mediated MDR cancers." (PMID 34326700, 2021). "Other anti-cancer drugs identified as ABCG2 substrates include flavopiridol, methotrexate, topotecan, and irinotecan." (PMID 33801813, 2021). "A potential approach to ameliorate Cancer MDR mediated by ABCG2 is co-administration of ABCG2 inhibitors with ABCG2 substrate antineoplastic drugs." (PMID 33829017, 2021). "We found that the efficacy of citarinostat on attenuating the HDAC6 deacetylase activity and the induction of apoptosis correspond directly to the reduced accumulation of citarinostat in ABCB1- and ABCG2-overexpressing human cancer cells." (PMID 33807514, 2021). "Exceptional medical relevance has the ABCG2 expression in cancer stem cells or drug-tolerant persisters, which can rapidly adapt to chemotherapy and repopulate the tumor." (PMID 33801813, 2021). "Some clinically used kinase inhibitors for cancer treatment are ABCG2 substrates and, therefore, act as competitive inhibitors of the transporter." (PMID 34545713, 2021).
cancer (continued). "AMG effectively and selectively inhibited ABCG2-mediated drug transport and reversed MDR in ABCG2-expressed MDR cancer cells." (PMID 34500560, 2021). "This indicates that sunitinib is mainly transported by ABCG2 and efficient inhibition of ABCG2 is needed in sunitinib-resistant cancer cells." (PMID 33953682, 2021). "The results of our study show that the novel compound, VKNG-1, significantly reverses MDR in S1-M1-80 cancer cells by blocking the efflux activity of the ABCG2 transporter and downregulating ABCG2 and p-AKT protein." (PMID 34572902, 2021). "Substrate recognition by ABCG2 has overlap with P-gp, but with some notable differences, including transport of the anti-cancer drugs flavopiridol, irinotecan, methotrexate, and mitoxantrone." (PMID 34993424, 2021). "On the contrary, a decrease in the stability of numerous transporters at the plasma membrane, such as ABCB1, ABCC1 (MRP1) or ABCG2 (BCRP), would be necessary to improve the efficiency of cancer treatments facing ABC transporter-mediated MDR." (PMID 33672718, 2021). "Here, we found that GBP5 knockdown decreased several chemotherapy resistance-associated cancer stemness markers such as ALDH1A1, ALDH1A2, CD44, CD166, and ABCG2." (PMID 34439200, 2021). "Among these three drugs, AZ-628, an RAF Kinase inhibitor, can reverse cancer multidrug resistance (MDR) by mediating ATP-Binding Cassette Transporter G2 (ABCG2)." (PMID 34737768, 2021). "Hoechst 33342, a DNA binding dye, can be pumped out by ABCG2, serving as the basis of side-population (SP) assay to identify CSCs in certain types of cancers." (PMID 33995678, 2021). "The ATP-binding cassette subfamily G member 2 (ABCG2) transporter is involved in the development of multidrug resistance in cancer patients." (PMID 34830383, 2021). "Our results revealed that at submicromolar concentrations, TP-3654 selectively reversed ABCG2-mediated MDR in ABCG2-overexpressing multidrug-resistant cancer cells in a concentration-dependent manner." (PMID 34502348, 2021). "Two other ABC transporters responsible for MDR in cancer cells are MDR-associated protein 1 (MRP1 or ABCC1) and breast cancer resistance protein (BCRP or ABCG2)." (PMID 33669953, 2021). "Upregulation of ABCC1-5, ABCB1, and ABCG2 is the main reason for the development of multiple drug resistance in various cancers by excreting chemotherapy drugs out of cancer cells." (PMID 33782384, 2021). "More recently, the anti-cancer drug imatinib was also found to lock the inward open structure of ABCG2." (PMID 34993424, 2021). "Among them, ABCB1 (P-gp, MDR1) and ABCG2 (breast cancer resistance protein, BCRP) have been identified as the major contributor to MDR in variety of cancers." (PMID 32670878, 2020). "Although expression of both ABCB1 and ABCG2 are commonly considered only in epithelial cells or cancer cells, the predominant expression of these pumps in prostate is in endothelial cells." (PMID 32584883, 2020). "5-FU-resistant cells appear to have cancer stem cell-like properties and express the drug transporter ABCG-2." (PMID 32629871, 2020). "ABCB1 and ABCG2 expression correlate with resistance to cisplatin and paclitaxel in cancer cells and in cells from patients and mice." (PMID 32157214, 2020). "We discovered that at submicromolar concentrations, sitravatinib re-sensitizes ABCB1- and ABCG2-overexpressing multidrug-resistant cancer cells to chemotherapeutic drugs." (PMID 31941029, 2020). "Our data indicate that erdafitinib is equally effective in treating ABCB1- and ABCG2-overexpressing multidrug-resistant cancer cells as drug-sensitive cancer cells." (PMID 32466597, 2020). "The RNA levels of Abcb1a, Abcg1 and Abcg2, some of the most studied drug transporters in cancer, were elevated in bGH and GHRKO mice, both of which have elevated circulating GH irrespective of the levels of IGF-1." (PMID 33291663, 2020).
cancer (continued). "EC16-1/saporin, at nanomolar concentrations, significantly inhibited the cellular proliferation of parental and ABCB1- and ABCG2-overexpressing cancer cells." (PMID 32098067, 2020). "To date, there is still no therapeutic agent approved by the U.S. Food and Drug Administration (FDA) for the modulation of ABCB1 or ABCG2 or treatment for patients with multidrug-resistant cancers." (PMID 31941029, 2020). "ABCG2 recognizes and transports a variety of chemotherapeutic drugs out of cancer cells, reducing drug concentration and resulting in drug resistance." (PMID 32577155, 2020). "Recent studies also demonstrate that the ABCG2 transporter is upregulated in certain populations of cancer stem cells and normal primitive stem cells in a manner that is correlated with resistance to various antineoplastic drugs." (PMID 32059437, 2020). "In a murine model system, EC16-1/saporin significantly inhibited the tumor growth in mice xenografted with parental and ABCB1- and ABCG2-overexpressing cancer cells." (PMID 32098067, 2020). "Expression of the major ABC transporters, including ABCA1, ABCB1, ABCC1, ABCC2, ABCC3 and ABCG2, was assessed in chemoresistant cancer cells transfected with si-ERRγ." (PMID 32206097, 2020). "The overexpression of ABCB1 and/or ABCG2 in cancer cells is known to contribute significantly to the development of multidrug resistance, an enormous challenge for scientists to overcome." (PMID 31941029, 2020). "ABCG2 overexpression can confer cancer cells resistant to a wide range of chemotherapeutic agents such as irinotecan, doxorubicin, and mitoxantrone." (PMID 32477940, 2020). "Nevertheless, the effect of regular treatment with erdafitinib on ABCB1 and ABCG2 in cancer patients remains to be further investigated." (PMID 32466597, 2020). "Our results indicated that our parental ABCB1- and ABCG2-overexpressing cells were an acceptable model to evaluate the anti-cancer and reversal efficacy of EC16-1/saporin." (PMID 32098067, 2020). "As an alternative, we and others have been investigating the potential repurposing of tyrosine kinase inhibitors (TKIs) as modulators of ABCB1 and ABCG2 to resensitize multidrug-resistant cancer cells to chemotherapeutic agents." (PMID 31941029, 2020). "Nevertheless, the effect of long-term regular treatment of sitravatinib on ABCB1 and ABCG2 in human cancer cells remains to be determined." (PMID 31941029, 2020). "Previous reports have demonstrated that ABCB1 and ABCG2 are capable of effluxing small molecule inhibitors of receptor tyrosine kinases (RTKs) such as sunitinib and imatinib out of cancer cells." (PMID 32466597, 2020). "Elevated ABCG2 expression in cancer cells results in resistance to a wide spectrum of chemotherapeutic agents, including mitoxantrone, topotecan, SN-38 and doxorubicin." (PMID 32085398, 2020). "Further, tivantinib showed a great ability to stimulate ABCG2 expression, suggesting the importance of monitoring the level of ABCG2 in cancer patients under tivantinib treatment." (PMID 31940916, 2020). "We hereby propose that BMS-599626 be considered for use in combination with substrates of ABCG2 to improve cancer therapy." (PMID 32899268, 2020). "Chemoresistance is often associated with elevated expression of drug efflux pumps, so we analyzed the expression of ABCB1/MDR1 and ABCG2, two major p-glycoproteins commonly up-regulated in cancer stem cells (CSCs)." (PMID 32477461, 2020). "Intriguingly, gefitinib further increases the elevated ABCG2 and cancer stem-like side population in HCC827GR cells, which can also be diminished by the FO and Se combination." (PMID 32751169, 2020). "Overall, our results indicated that MCA's efficacy in ABCB1- and ABCG2-overexpressing and cisplatin resistant cancer cells is due to the induction of apoptosis and cell cycle arrest in the G0/G1 phase." (PMID 32676451, 2020).
cancer (continued). "Flow cytometry experiments to isolate the ABCG2+ subpopulations of HCC cell lines sub-cultured for 4 weeks revealed the presence of both ABCG2+ and ABCG2− progenies, supporting critical roles of ABCG2 in maintenance of the cancer cell hierarchy of HCC." (PMID 32466488, 2020). "In the present study, we report the potential interactions of sitravatinib with ABCB1 and ABCG2 in human multidrug-resistant cancer cells." (PMID 31941029, 2020). "Incubation with 3 μM of AZ-628 significantly increased the intracellular accumulation of ABCG2-substrate [3H]-mitoxantrone in both ABCG2-overexpressing cancer cells H460/MX20 and S1-M1-80." (PMID 33364237, 2020). "In the present study, we investigated the effect of sitravatinib, a novel multitargeted receptor tyrosine kinase inhibitor, on human ABCB1 and ABCG2 in multidrug-resistant cancer cell lines." (PMID 31941029, 2020). "In accordance with the increase of ABCG2, a molecular determinant of the side-population phenotype, the proportion of cancer stem-like side population in the HCC827GR cells was raised to 2.53% from 0.3% of the parental HCC827." (PMID 32751169, 2020). "The levels of cancer stemness-related genes (ABCG2, BMI1, NANOG, KLF4, and OCT4) mRNA and proteins (ABCG2, Oct4, Bmi-1, and CD44) expression were downregulated with treatment of STF-31 in HBx-expressing MHCC-97H cells." (PMID 32168902, 2020). "ABCG2 overexpression can render cancer cells resistant to conventional chemotherapeutic agents, in particular topotecan, irinotecan, mitoxantrone, and doxorubicin, making it a prominent factor leading to MDR." (PMID 32477940, 2020). "The most relevant ABC transporters expressed by brain endothelial cells are P-glycoprotein (P-gp, ABCB1), breast-cancer-related protein (BCRP, ABCG2), and the multiple drug-related proteins (MRP1, -4, -5; ABCC1, -4, -5)." (PMID 33322488, 2020). "We then analyzed by RT-qPCR the expression of the different markers involved in the cancer stem cells’ biology (Sox2, Oct3/4, Notch1, Nanog, Abcg2, Aldh1a1 and Aldh1a3)." (PMID 32610610, 2020). "Patients with this type of cancer often develop brain metastases, which are difficult to treat with erlotinib, most likely due to its low brain distribution caused by ABCB1/ABCG2-efflux transport at the BBB." (PMID 33153231, 2020). "Next, we examined the chemosensitizing effect of erdafitinib in multidrug-resistant cancer cells overexpressing ABCB1 or ABCG2." (PMID 32466597, 2020). "Doxorubicin is a DSB‐inducing radiomimetic agent and is widely used as a cytotoxic drug in cancer treatment, but its retention in cells is also influenced by the expression of membrane efflux pumps such as ABCG2." (PMID 32333827, 2020). "These substrate drugs have attenuated the antineoplastic efficacy in ABCG2-overexpressing cancer cells." (PMID 31940916, 2020). "Overexpression of ABCG2 remains a major impediment to successful cancer treatment, because ABCG2 functions as an efflux pump of chemotherapeutic agents and causes clinical multidrug resistance (MDR)." (PMID 33364237, 2020). "Clinically, ABCG2 has been detected in various cancer cells including breast, lung, bladder, and colon cancers." (PMID 33364237, 2020). "ABCG2 has been suggested to be involved in clinical multidrug resistance (MDR) in cancer, and we found that ABCG2 was activated by CTCF in CRC." (PMID 32688344, 2020). "This study suggests that NVP-TAE684 reverses ABCG2-mediated MDR by inhibiting the efflux activity of cancer cells, therefore increasing intracellular concentration of chemotherapeutic drugs." (PMID 32175279, 2020). "On the other hand, ABCG2 is involved in MDR in cancer chemotherapy therefore, caution should be exercised when co-administering prenylflavonoid-rich foods/dietary supplements with ABCG2 substrates." (PMID 32937790, 2020).